INS (insulin)
Diseases named in the same sentence as INS in open-access papers (continued):
Sharing a sentence is not in itself a finding about the gene and the disease.
Insulin resistance (continued). "Disruption of FAK increased insulin resistance in both male and female aP2FAK−/− mice as seen by elevated fasting serum insulin levels, increased β-cell to pancreas area and insulin tolerance testing (ITT), without changes in glucose tolerance." (PMID 28165007, 2017). "The index of homeostasis model assessment-estimated insulin resistance, insulin, and free fatty acid concentrations were higher in db/db mice compared with wild-type." (PMID 29152121, 2017). "This disease is strongly associated with obesity and insulin resistance and has revealed mechanisms of insulin resistance that target the either impairs in β-cell function or insulin insensitive action at adipose tissue, skeletal muscle, or liver tissues." (PMID 29099085, 2017). "High-fructose diets commonly induce systemic insulin resistance and fasting hyperinsulinemia, thereby promoting insulin-mediated SREBP1c activation and hepatic lipid synthesis." (PMID 28878197, 2017). "With proinflammatory cytokines binding to responding receptors, insulin signaling pathways were interfered, and abnormal insulin secretion and insulin resistance emerged." (PMID 28217099, 2017). "Our laboratory has previously shown that tissue-specific intestinal GU from circulation into enterocytes is impaired in the insulin-stimulated state, i.e., intestinal insulin resistance exists, in obese and type 2 diabetic subjects." (PMID 28183816, 2017). "Women with GDM have a combination of acquired and chronic insulin resistance and are more insulin resistant compared to the normal women during late pregnancy." (PMID 28732072, 2017). "To investigate the further mechanisms of ADSC transplantation on insulin resistance, we used a q-PCR analysis method to evaluate the expression of insulin resistance-related genes, including IRβ and IRS1, as well as IRS2 and GLUT2 in the liver tissues." (PMID 29258603, 2017). "Elevated insulin levels, insulin resistance, obesity and the initially moderate rise of blood glucose levels in T2D are amongst the factors that need to be considered during evaluation." (PMID 28827737, 2017). "Research conducted with the intention of observing relationships with ncRNAs and insulin resistance has revealed certain relationships such as miRNAs in the β-cell development and its functions, insulin production, insulin secretion, and glucose homeostasis." (PMID 29057258, 2017). "That impairment of insulin clearance plays a significant role in hepatic insulin resistance in response to high-fat diet has recently been demonstrated in Asian men." (PMID 28184213, 2017). "SH-SY5Y neuroblastoma cells treated with high concentration of insulin displayed insulin resistance with reduced pAkt level." (PMID 28282917, 2017). "In accordance, infusion of EETs with mini-pump attenuated HFD induced insulin resistance characterized by decreased plasma glucose and insulin levels, improved insulin sensitivity by GTT and ITT, and preserved insulin-induced Akt phosphorylation level." (PMID 28440284, 2017). "Other studies have reported aberrant cerebral insulin homeostasis, which is called insulin resistance, in AD patients." (PMID 29165354, 2017). "The presence of brain insulin resistance and the hyperphosphorylation of tau found in this model makes it very useful for investigating the effects of insulin on tau hyperphosphorylation." (PMID 28382978, 2017). "Insulin resistance usually refers to a defect in the ability of insulin to stimulate glucose uptake and is a characteristic feature of DM, obesity, and other metabolic diseases." (PMID 28708100, 2017). "This is partly because increases in body weight can lead to increases in insulin resistance as well as defects in insulin secretion." (PMID 28572982, 2017).
Insulin resistance (continued). "In contrast, post-intervention levels of glucose, insulin, C-peptide and insulin resistance were significantly lower than baseline in the probiotics group (p < 0.01, < 0.01, 0.01 and < 0.01, respectively)." (PMID 29228964, 2017). "Insulin resistance is characterised by impaired cellular response to insulin, and the inability of physiological levels of insulin to achieve glucose homeostasis." (PMID 29050364, 2017). "Glucose uptake enhanced in adipocytes after stimulation with CuE and insulin resistance diminished in mice treated with CuE, as reflected by reduced glucose intolerance and glucose stimulated insulin secretion." (PMID 28598969, 2017). "This outcome suggests partial insulin resistance, with hepatic insulin sensitivity retained while other tissues (presumably skeletal muscle) are insulin resistant." (PMID 28360832, 2017). "Insulin resistance is defined as decreased tissuesensitivity to insulin to stimulate glucose uptake and utilisation." (PMID 28290272, 2017). "Levels of the pro-inflammatory cytokine, TNFα, a potent inhibitor of insulin signaling and therefore a major contributor to insulin resistance, are elevated in obese subjects." (PMID 29104232, 2017). "Levels of irisin also correlate with reactive oxygen species, which play an important role in the development of insulin resistance and metabolic syndrome and are required for basal insulin signaling." (PMID 28658348, 2017). "The development of insulin resistance in multiple tissues and impaired insulin secretion by pancreatic β-cells in response to glucose are the two main pathophysiologic characteristics of type 2 diabetes." (PMID 28606124, 2017). "Adhering to three indirect indexes used to predict insulin sensitivity, both F. deltoidea and vitexin had a significant impact in lowering insulin resistance." (PMID 28576138, 2017). "The maternal high-fat fed offspring showed increased insulin sensitivity inapposite to the elevated insulin resistance in their mothers, as also reported in the researchers’ previous study." (PMID 28261314, 2017). "A novel data provided in our study was the association between fructose consumption and long-term changes of serum insulin and insulin resistance index, as the well-known criteria for assessment of insulin/glucose homeostasis." (PMID 28825653, 2017). "We found that AI efficiently reversed the HFD-induced insulin resistance in mice as the fasting plasma levels of insulin and glucose and the AUC value from oral glucose loading were all significantly decreased." (PMID 28805698, 2017). "Pde3b-knockout mice exhibited multiple alterations in regulation of lipolysis, lipogenesis, and insulin secretion, as well as signs of peripheral insulin resistance." (PMID 28430825, 2017). "Enhanced insulin response showed a beginning of insulin-resistance, which was concomitant to a higher degree of OC decarboxylation." (PMID 28806419, 2017). "There was clear evidence of insulin resistance in test rats of the NASH model as fasting insulin levels (FINS), free blood glucose (FBG), and homeostasis model assessment of insulin resistance (HOMA-IR) increased significantly." (PMID 28255329, 2017). "Insulin resistance and increased plasma insulin concentration were also observed in obese individual." (PMID 28578702, 2017). "First, the capability of the extract to reduce serum insulin and insulin resistance was shown; however, the results also showed that the purer the mixture, the lower the bioactivity to inhibit glucosidase." (PMID 28970780, 2017). "T2DM is characterized by elevated fasting plasma glucose (FPG), insulin resistance, increased hepatic glucose production (HGP), and a deficiency in glucose-stimulated insulin secretion (GSIS)." (PMID 28191470, 2017). "Further, 8 wk blueberry supplement decreased markers of oxidative stress in obese men and women with the MetS and improved insulin sensitivity in obese subjects with insulin resistance." (PMID 29141041, 2017).
Insulin resistance (continued). "High-fat diet (HFD)-induced obesity is accompanied by insulin resistance and compromised brain synaptic plasticity through the impairment of insulin-sensitive pathways regulating neuronal survival, learning, and memory." (PMID 28710347, 2017). "Experimental studies in animal models and in humans show that overexposure of lean-tissues to fatty acids plays an important role in the development of insulin resistance and impaired insulin secretion by a process called lipotoxicity." (PMID 28606124, 2017). "Insulin resistance, the inability of peripheral tissues to properly respond to insulin, is initially compensated by a rise in insulin output in order to maintain normoglycemia." (PMID 28950020, 2017). "The ratio of plasma TG/HDL-C was the best predictor of insulin resistance, which was determined by the steady-state plasma glucose concentration during the insulin suppression test." (PMID 28549070, 2017). "One promising avenue for future research is in using intranasal insulin in combination with neuroimaging methodologies and neuropsychological testing to assess the role of central insulin resistance in neurocognition." (PMID 28400713, 2017). "Insulin resistance is a central feature of type 2 diabetes, which results from reduced responsiveness of insulin target tissues such as liver, adipose and muscle to normal insulin levels." (PMID 29362600, 2017). "The HOMA models mostly reflect hepatic insulin resistance and steady-state insulin secretion as they use fasting values for estimation." (PMID 28409212, 2017). "This phosphorylation has been demonstrated in adipocytes in vitro, indicating that IKKβ contributes to insulin resistance by attenuating the insulin signaling immediately at the postreceptor level." (PMID 28912810, 2017). "The macrophages in adipose cells secrete proinflammatory cytokines (adipocytokines) such as C-reactive protein, interleukin (IL)–6, IL-8, IL-10, and tumor necrosis factor–α; these cytokines impair insulin signaling, inducing insulin resistance." (PMID 28234943, 2017). "Catecholamines, acting through ß-activation, inhibit insulin action in fat cells and thereby promote insulin resistance." (PMID 28346464, 2017). "Afterwards, the reduced insulin sensitivity of adipose tissue breaks the balance of systemic glucose metabolism, which manifests as hyperglycemia, insulin resistance and glucose intolerance." (PMID 29057818, 2017). "We aimed to compare the effects of plasma glucose levels, plasma insulin levels and insulin resistance on the appearance of the AD-like pattern in 18F-FDG images." (PMID 28715453, 2017). "This difference in fat partitioning has been attributed to increased insulin resistance with concomitant decreased insulin sensitivity in these individuals." (PMID 29165385, 2017). "The insulin tolerance test revealed impaired insulin sensitivity in IH compared to control mice, which confirmed a systemic insulin resistance." (PMID 28255159, 2017). "In the present study, we have isolated SeP-neutralizing Abs that improve glucose intolerance, insulin resistance and insulin secretion in vitro and in vivo." (PMID 29162828, 2017). "T2DM is a complex heterogeneous group of metabolic disorders resulting in high blood glucose due to impaired insulin secretion or insulin resistance." (PMID 29089569, 2017). "The PI3K-Akt signaling pathway exhibited the highest number of target connections (degree = 13), followed by insulin resistance with 12 targets, insulin signaling pathway and HIF-1 signaling pathway with 11 ones, respectively." (PMID 29051733, 2017). "To disclose the potential relation between the increased circulating FFAs and insulin resistance, we investigated lipid deposits and insulin signaling in skeletal muscle." (PMID 28261091, 2017). "Alterations in signal molecules involved in insulin signaling evidently play a major role in insulin resistance seen in type 2 diabetes." (PMID 28642704, 2017).
Insulin resistance (continued). "The main pathophysiology is insulin resistance that stresses the pancreatic β-cells to augment insulin secretion and is triggered by obesity and physical inactivity." (PMID 28654680, 2017). "Hepatic insulin resistance is characterized by impaired insulin-mediated suppression of glucose production, whereas adipose tissue insulin resistance is characterized by impaired insulin-mediated suppression of lipolysis." (PMID 28587303, 2017). "Insulin levels were measured concomitantly and insulin resistance markers were evaluated (HOMA 2-IR, Insulin Sensitivity Index for glycemia (ISI-gly))." (PMID 28497040, 2017). "The plasma insulin level in obese subjects is increased approximately 2- to 3-fold to compensate insulin resistance, and an increase in beta cell mass with obesity is assumed." (PMID 29483484, 2017). "A higher fasting insulin concentration indicates insulin resistance, a well-known contributor to impaired glucose tolerance and T2DM." (PMID 28891932, 2017). "While impaired insulin secretion and insulin resistance are the main pathophysiological mechanisms of type 2 diabetes, little is known of the relative contribution of these factors to glucose intolerance in patients with NAFLD." (PMID 28878826, 2017). "In fact, progression to IGT in adults is characterized by insulin resistance and the inability of the β-cells to adequately compensate for high blood glucose levels through increased insulin secretion." (PMID 28531113, 2017). "LLAE also significantly reduced visceral fat mass, decreased fasting serum insulin levels and ameliorated insulin resistance in HFD-induced obese rats, indicating the anti-obesity and anti-diabetic activity of LLAE." (PMID 28690544, 2017). "Insulin resistance, along with a defect in insulin secretion by the pancreatic β cells is instrumental towardsprogression to hyperglycemia." (PMID 29379255, 2017). "When ATG7 is repressed in livers of lean mice, they develop severe insulin resistance, which also suggests a role for autophagy in insulin action." (PMID 28768896, 2017). "One of the important pathologic characteristics of T2D is insulin resistance, which is resulted from impairment of insulin signaling pathway." (PMID 28698587, 2017). "Consistent with this, Stat5Adipoq mice displayed reduced insulin resistance scores and improved insulin sensitivity in ITTs." (PMID 27858140, 2017). "The same pathway allowed to discriminate between insulin resistance and insulin sensitive subjects with BMI >25, supporting his role as a biomarker of IR." (PMID 28777829, 2017). "It is known that diet-induced obesity, in mice, also provokes glucose intolerance accompanied by increased insulin secretion, which compensates for the peripheral insulin resistance." (PMID 28951790, 2017). "In conclusion, the HFHF diet-fed pigs developed isolated impaired glucose tolerance corresponding to prediabetes with an intense insulin secretory response and skeletal muscle insulin resistance." (PMID 29046729, 2017). "Of note, the increased body weight gain was possibly due to attenuated adipose insulin resistance, as we found MCFAs reactivated insulin-induced Akt phosphorylation in adipose tissues of HFD-fed mice." (PMID 29070903, 2017). "Data collected concerned the body mass index, waist circumference, systolic blood pressure, diastolic blood pressure, fasting blood glucose, plasma lipids, adiponectin, leptin, insulin and homeostasis model for assessment of insulin resistance (HOMA-IR)." (PMID 28878827, 2017). "Despite the possible involvement of the GNDPA2, TMEM18, and ADCY3 loci in insulin resistance, insulin/glucagon regulation, and insulin secretion, respectively, we chose to retain them in the IV analysis." (PMID 28763444, 2017). "The aim of this study was to investigate the insulin secretory response and tissue-specific insulin resistance in a dietary-induced prediabetic porcine model." (PMID 29046729, 2017).
Insulin resistance (continued). "Insulin resistance (IR) is a common pathophysiological condition in which patients present with reduced insulin sensitivity and thus glucose intolerance, particularly in liver, adipose tissue and skeletal muscle." (PMID 29157234, 2017). "The eGDR has been validated as an easy method to evaluate insulin resistance in type 1 DM, with higher values indicating increased insulin sensitivity." (PMID 28225861, 2017). "It has been revealed that T2DM develops when the insulin secretory capacity is unable to compensate for the increase of insulin resistance." (PMID 28333091, 2017). "They found a positive association of high-nocturnal-melatonin secretion with greater insulin sensitivity and a lower prevalence of insulin resistance in healthy young women." (PMID 29142618, 2017). "HFD-fed mice exhibited hypercholesterolaemia, obesity and insulin resistance as determined by measurement of plasma lipids and insulin levels and intraperitoneal insulin tolerance (IP-ITT) and glucose tolerance test (IP-GTT)." (PMID 27933336, 2017). "Previously reported study has confirmed that abdominal obese release excessive free fatty acids, which are transported to the liver and pancreas and reduced response to insulin signaling (i.e. insulin resistance)." (PMID 29262577, 2017). "Another study demonstrated that CU resulted in reduced fasting insulin, insulin resistance, smaller waist circumference and higher levels of HDL." (PMID 28441459, 2017). "Insulin levels were higher in the diabetic group due to insulin resistance as a result of high glucose levels in blood." (PMID 28116330, 2017). "Insulin resistance in skeletal muscle is manifested as a decrease in glucose transport and a decline in muscle glycogen synthesis in response to circulating insulin." (PMID 28848738, 2017). "It is hard to build a model that emerges simultaneously all features of obesity complicated with hyperlipidemia, insulin resistance, mild high blood glucose, and high-insulin hematic disease." (PMID 29404372, 2017). "It has been established that insulin levels and the frequency of insulin resistance increase as puberty progresses." (PMID 27598976, 2017). "Since pubertal-associated insulin resistance resolves following puberty and PCOS adult women are more insulin resistant than control women, it is expected that glucose and NEFA metabolism in at-risk and controls will segregate again beyond young adulthood." (PMID 28738839, 2017). "Increased postprandial glucose and insulin levels as a result of insulin resistance and decreased postprandial ghrelin levels have been demonstrated in patients with cirrhosis and were found to correlate with prolonged small intestinal transit." (PMID 28584525, 2017). "It has been reported that the CPAE can improve insulin resistance by affecting the insulin-signaling pathway in peripheral tissue." (PMID 28684967, 2017). "Our study confirmed that serum adropin levels negatively correlated with the levels of TG, fasting glucose, and insulin as well as insulin resistance and positively correlated with HDL-C levels." (PMID 29255252, 2017). "Insulin resistance (IR) can be broadly defined as a reduced cellular responsiveness to insulin, characterized by higher insulin levels needed to maintain glucose levels in the periphery and brain." (PMID 28093279, 2017). "Taken together, these results demonstrate that miR-291b-3p contributed to hyperglycemia and hepatic insulin resistance through suppressing insulin-stimulated AKT/GSK signaling activation and increasing expression of gluconeogenic genes in hepatocytes." (PMID 28054586, 2017). "Insulin resistance refers to the situation where the target cells lose response to insulin stimulation and thus reduce glucose uptake." (PMID 29209160, 2017). "For instance, Nrf2 regulates blood glucose homeostasis and metabolic reprogramming by redirecting anabolic pathways, inhibiting lipogenesis, and promoting insulin sensitization, thereby ameliorating insulin resistance." (PMID 28913364, 2017).